CXCL2 (C-X-C motif chemokine ligand 2)
Diseases named in the same sentence as CXCL2 in open-access papers (continued):
Sharing a sentence is not in itself a finding about the gene and the disease.
gout (5 papers, 2017 to 2025). A condition characterized by painful swelling of the joints, which is caused by deposition of urate crystals. "Since IL-1β and IL6 have been linked to gout in numerous studies, our main focus was on the connection between CXCL8, CXCL1, and CXCL2 and acute gouty arthritis." (PMID 38686389, 2024). "Studies on the role of CXCL2 in gout are rare, although CXCL2 has a chemotactic effect on neutrophils during MSU crystal-induced neutrophil migration." (PMID 38686389, 2024). "The ability of the ceRNA network to predict miRNAs and lncRNAs upstream of CXCL8, CXCL1, CXCL2, IL-1β, and IL6 may lead to the use of a novel diagnostic and prognostic marker for gout." (PMID 38686389, 2024). "In summary, CXCL8, CXCL1, and CXCL2 may be gout biomarkers, and this research may lead to novel approaches for the clinical management of individuals with gouty arthritis." (PMID 38686389, 2024). "The upregulation of genes like”IL1B”and”CXCL2”in CD14+ monocytes further supports their involvement in the activation of the NLRP3 inflammasome, a critical pathway in gout pathogenesis." (PMID 40370447, 2025). "Previous studies have found an increased expression of various chemokines (including CXCL8, CCL3, CXCL2, and MCP-1) in stimulations with MSU crystals in experimental models of gout or in the serum of gout patients." (PMID 36979628, 2023). "Our findings could lead to the development of new approaches for the treatment of gout; however, the precise regulatory mechanisms of CXCL8, CXCL1, and CXCL2 in gout remain unclear." (PMID 38686389, 2024).
Hypertension (5 papers, 2021 to 2025). The presence of chronic increased pressure in the systemic arterial system. "Patients who had improved hypertension 6 months after surgery presented with increased expression levels of the inflammasome activation components (ASC, P2X7, and IL18R), cytokines (CCL8, CXCL2, IKKA, and IL6R), NOD-like receptors (NLRP1), and cell cycle/DNA regulators (TGFb)." (PMID 37867510, 2023). "In addition, the comparison of OSA patients without any other disease with OSA patients with only hypertension also demonstrated increased levels of CXCL2/GRO-ß and IL-7." (PMID 36769452, 2023).
liver fibrosis (5 papers, 2021 to 2025). "In IL-37 transgenic mice with BDL-induced liver fibrosis, reduced expression levels of early liver fibrosis markers, such as C-X-C Motif Chemokine Ligand 2, were observed, along with decreased collagen deposition and liver fibrosis." (PMID 39995661, 2025). "Here, our results indicated that MyD88 in macrophages activates HSCs through CXCL2 secretion and promotes liver fibrosis." (PMID 34830293, 2021). "In accordance to histologically overt liver fibrosis, Cxcl2 gene expression as an early marker of liver fibrosis 3 days after BDL was significantly higher in Wt compared to sham-operated mice." (PMID 33746950, 2021). "CXCL2 may be a promising target for the prevention and treatment of liver fibrosis." (PMID 34830293, 2021). "However, studies that focus on the relationship between CXCL2 and liver fibrosis are rare." (PMID 34830293, 2021). "To further investigate the role of CXCL2 in liver fibrosis, we examined the therapeutic potential of a CXCR2 inhibitor in a mouse liver fibrosis model." (PMID 34830293, 2021). "Consistently, the mRNA levels of inflammatory mediators TNF-α and IL-1β, as well as IL-6, ICAM, CCL2, CXCL2, and TGF-β, which were indicated as progressive inflammatory response and liver fibrosis, were significantly elevated in the liver of MFG-E8 knockout mice compared with the MCD-WT group." (PMID 35769208, 2022). "Moreover, targeting CXCL2 by CXCR2 inhibitors attenuated the activation of HSCs and reduced liver fibrosis." (PMID 34830293, 2021). "Furthermore, MyD88 in macrophages enhanced CXCL2 secretion and activated NLRP3 inflammasome in HSCs, which in turn promoted liver fibrosis." (PMID 34830293, 2021). "The expression of Fcgr2b and Spp1 was increased only in aggravated fatty liver, and the expression levels of Cxcl2 and Elane increased when liver fibrosis occurred which is not completely reversible, suggesting that these genes may play a key role in the prognosis of NAFLD." (PMID 36426356, 2022).
malaria (5 papers, 2014 to 2025). Malaria is a serious and sometimes fatal disease caused by a parasite that commonly infects a certain type of mosquito which feeds on humans. "We observed increased IL-4, CXCL1, CXCL2, and CCL4 within the placenta, which have all been reported to be increased in humans, mice, or in vitro models of malaria (49, –, 52)." (PMID 40470930, 2025). "In addition to producing type I IFNs, DCs produce a wide range of pro-inflammatory cytokines, including TNF-α, IL-12, and IL-6, and chemokines, such as CXCL1, CXCL2, CCL2, CCL5, CXCL9, and CXCL10 in response to malaria parasites, and play crucial roles in malaria immunity and pathogenesis." (PMID 30619355, 2018).
meningitis (5 papers, 2018 to 2025). A disorder characterized by acute inflammation of the meninges of the brain and/or spinal cord. "The signal for the CXCL2 expression, in contrast, was only enhanced for some piglets suffering from meningitis." (PMID 33763387, 2021). "CXCL2 CSF concentration in non-TBE meningitis was elevated (p < 0.05) and not different from the TBE group." (PMID 29678185, 2018). "Subsequent RT-PCR analyses confirmed our assay results: CL-treated meningitis animals showed higher expression levels of CCL2 and CXCL2 (but not GFAP) compared to PBSL-treated mice." (PMID 40988032, 2025).
prostate tumor (5 papers, 2007 to 2022). "Similarly, several studies have linked marrow fat cells-derived CXCL1 and CXCL2 chemokines with prostate tumor progression and the effects of osteolysis in metastatic prostate cancer." (PMID 35498437, 2022). "The baseline and radiation-enhanced secretion of CXCL8 (and its orthologues CXCL1, CXCL2 and CXCL5) from PTEN-deficient prostate tumour epithelial cells exerts both autocrine and paracrine actions within the tumour microenvironment given the expression of CXCR1 and CXCR2 upon multiple cell types." (PMID 32743555, 2020). "Quantified by ELISA, we detected that CXCL2 and CXCL3 protein levels were elevated in peripheral blood and prostate tumors of PtenPC−/−; Arid1aPC−/− mice relative to that in PtenPC−/− mice." (PMID 36435834, 2022). "Taken together, these results suggest that HFD-induced increases in the production of soluble factors (MCP-1, CXCL1, CXCL2, and CXCL13) play important roles in the stimulation of prostate tumor progression in mice." (PMID 25912035, 2015).
systemic lupus erythematosus (5 papers, 2014 to 2022). An autoimmune multi-organ disease typically associated with vasculopathy and autoantibody production. "Perhaps the most prominent effect was in its normalization of plasma cytokines, several of which, such as CCL5/RANTES, CXCL2/MIP-2, CXCL12/SDF-1α, and CXCL13/BCA-1, were known biomarkers of lupus severity." (PMID 32582860, 2020). "In systemic lupus erythematosus (SLE), downregulation of miR-4512 leads to high expression of TLR4 and CXCL2 in macrophages, which release more pro-inflammatory factors." (PMID 35634335, 2022).
amoebiasis (4 papers, 2022 to 2024). "For example, lncRNA BX470102.1 is involved in amoebiasis, Kaposi sarcoma-associated herpesvirus infection, TNF signaling pathway, and IL-17 signaling pathway by targeting multiple target genes such as IL-6, CXCL2, and PTGS2." (PMID 36457749, 2022).
brain ischemia (4 papers, 2013 to 2025). Diminished or absent blood supply to the brain caused by obstruction (thrombosis or embolism) of an artery resulting in neurologic damage. "CXCL2+neutrophils at the border of the brain are rapidly generated and infiltrated into the brain following cerebral ischemia to promote the production of neutrophil extracellular traps, exacerbating the no‐reflow phenomenon and hampering recovery after cerebral ischemia." (PMID 39135337, 2024).
Breast tumor (4 papers, 2011 to 2025). "One gene, CXCL2, showed decreased expression in the breast tumors arising in young versus older women (Fold Change -1.35, p = 0.052)." (PMID 25999348, 2015). "Breast tumors produce various factors, such as G-CSF, granulocyte/macrophage stimulating factor (GM-CSF), IL-6, IL-1β, IL-17, TGF-β, C-X-C motif chemokine 2 (CXCL2; encoded by CXCL2), C-X-C motif chemokine 5 (CXCL5; encoded by CXCL5), and CCL2." (PMID 41550427, 2025). "Breast tumor cells and ES cells secrete cytokines and chemokines to their microenvironment, however, breast cancer cells secrete a significantly higher level of soluble factors, which is correlated with tumor metastasis (e.g., M-CSF, OSM, MIP-2/CXCL-2, MMP-9, TIMP-1)." (PMID 22174624, 2011).
depression (4 papers, 2019 to 2024). "The CXCL1 chemokine deletion can cause rat depression-like behaviors, and CXCL1/CXCL2 correlates with depression-like behavior in response to chronic stress." (PMID 35711916, 2022). "CXCL2, also recognized as macrophage inflammatory protein-2 alpha (MIP-2 α), growth-regulated protein beta (GRO-β), and growth oncogene-2 (Gro-2), is a small chemokine expressed in various cells, such as microglia, astrocytes, and neurons and plays an important role in inflammation and depression." (PMID 38674048, 2024). "In a model of major depressive disorder, TNF-α expression is increased, and an antidepressant treatment decreases the expression of ADAM17 and its targets CXCL2 and IL-6." (PMID 30586315, 2019).
fibrosis (4 papers, 2021 to 2023). the formation of excess fibrous connective tissue in an organ or tissue in a reparative or reactive process. "The expression levels of CCL2 and CXCL2 were significantly lower in the lungs of BLM-induced NFATc3+/- fibrosis mice compared to those of NFATc3+/+ mice." (PMID 37523510, 2023). "Isolated lung macrophages from bleomycin-treated mice expressed increased Cxcl2 mRNA compared with lung macrophages from saline-treated mice, suggesting that tissue-resident macrophages may play a role in neutrophil recruitment to the airspaces in fibrosis." (PMID 36534439, 2022).
gastritis (4 papers, 2015 to 2025). Inflammation of the stomach. "Of which, MMP9, CXCL2, CXCL8, and IL-10 were part of the 15 common genes, and these four genes are significantly upregulated between gastritis patients and normal control." (PMID 34471638, 2021). "PTGS2, NOS2, EGFR, MMP9, CXCL2, CXCL8, and IL-10 may be the important direct targets of Weibing Formula 1 in gastritis treatment." (PMID 34471638, 2021). "In addition to IL-10, MMP9, CXCL2, and CXCL8 expression levels were significantly increased in gastritis patients compared with the control group, which was consistent with the GSE60427 and GSE5081 results." (PMID 34471638, 2021). "In conclusion, the potential mechanism of Weibing Formula 1 in treating gastritis has the multicomponent, multitarget, and multiway characteristics, and PTGS2, NOS2, EGFR, MMP9, CXCL2, CXCL8, and IL-10 may be the important direct targets of Weibing Formula 1 in gastritis treatment." (PMID 34471638, 2021).
Hepatic steatosis (4 papers, 2013 to 2025). Steatosis is a term used to denote lipid accumulation within hepatocytes. "The administration of HCD in piglets has been associated with hepatic steatosis, insulin resistance, and hepatic inflammation, including increased myeloperoxidase activity and expression of proinflammatory cytokines and chemokines, particularly IL-2, CXCL2, TNFα, and IL-6." (PMID 23565157, 2013).
inflammatory bowel disease (4 papers, 2015 to 2026). A spectrum of small and large bowel inflammatory diseases of unknown etiology. "The inflammation and inflammatory bowel disease (IBD) disorders had many commonly modulated genes that were also found in the String analysis that were common with the disorders which included IL-8, ICAM1, RELB, NFκBIA, TNFAIP3, LIF, CXCL1, CXCL2, CXCL3, CXCL10, and TNF-α." (PMID 28099447, 2017).
ischemic stroke (4 papers, 2015 to 2024). A stroke disorder caused by obstruction of blood flow to the brain, due to thrombotic (local blood clot formation) or embolic (due to a blood clot or other material traveling from another site) event. "In our study, we observed that CXCL2+ neutrophils of cerebral border origin had an enhanced ability to form NETs, which impaired vascular reperfusion after ischemic stroke." (PMID 39135337, 2024). "Here, we showed that ischemic stroke‐induced expansion of CXCL2+ neutrophils, which exhibit highly proinflammatory features." (PMID 39135337, 2024). "In this study, we found that cerebral ischemic stroke triggered expansion of CXCL2+ neutrophils in the brain border, which were NETosed and potentially mediated incomplete reperfusion post‐ischemic stroke." (PMID 39135337, 2024). "Among the upregulated genes, Hspa1b, Ccl2, Cxcl2, Ccl3, Serpina3n, Timp1, H19, Hspb1, Ccl20, and Cxcl1 were found to demonstrate significant upregulation in pathological phase of ischemic stroke." (PMID 25861363, 2015). "Our results expand the understanding of the role of brain border‐associated myeloid cells in exacerbating ischemic stroke and propose novel treatment that targets CXCL2+ neutrophils for no‐flow‐related neurological deficits following cerebral ischemic stroke." (PMID 39135337, 2024). "Collectively, brain border‐derived CXCL2+ neutrophil expansion may impair vascular reperfusion by releasing NETs following ischemic stroke." (PMID 39135337, 2024). "Our study provides new insights that targeting CXCL2+ neutrophils generated by meninges could be a potential treatment for improving vascular reperfusion following ischemic stroke." (PMID 39135337, 2024). "We tracked CXCL2+ neutrophils in vivo by utilizing a photoconvertible Kik‐GR mouse (fluorescent proteins Kikume Green Red, Kik‐GR) and found that brain‐infiltrating CXCL2+ neutrophils following ischemic stroke were mainly derived from the brain border rather than the periphery." (PMID 39135337, 2024).
legionellosis (4 papers, 2019 to 2024). Any disease caused by Legionella bacteria. "The results revealed three up-regulated genes (SEC22B, CXCL2, and CYCS) and two down-regulated genes (CA3, CA4) were significantly involved in Legionellosis and nitrogen metabolism pathways, respectively." (PMID 32174961, 2020).
metastatic disease (4 papers, 2013 to 2022). "We further screened core genes using the protein interaction network of the STRING database and found that CXCL2 was an important core gene of lung metastatic tumours." (PMID 35541899, 2022).
myeloma (4 papers, 2020 to 2024). "Remarkably, only CXCL2 conformed to the differential expression pattern observed in patients with multiple myeloma." (PMID 39040102, 2024). "ChIP-on-chip data revealed that heparanase bound to regulatory regions of myeloma-related genes (i.e., CXCL12), encodes for SDF-1, CXCR4, CXCL2, CXCR3, CCL27, CX3CL1, and LCN2." (PMID 36980254, 2023). "When we added the inhibitor specific for ERK1/2, STAT1, STAT3, or Akt to cocultures of myeloma cells and MSCs, we found that the kinase inhibitor alone or in combination reduced the expression of CXCL1, CXCL2, SDF1, and MCP1 in myeloma cells." (PMID 34150666, 2021).
osteomyelitis (4 papers, 2014 to 2026). An acute or chronic inflammation of the bone and its structures due to infection with pyogenic bacteria. "We identified that significant infiltration of Arg1+Sdc4+, Cxcl1+Ccl4+, and Mif+Cd63+ macrophages may affect osteomyelitis through the Ccl3-Ccr1 and Cxcl2-Cxcr2 signaling pathways." (PMID 41836400, 2026). "Besides, in osteomyelitis, the expression of macrophage-related inflammatory proteins CXCL2 (MIP2α) and CCL3 (MIP1α) is related to the inflammation and bone degradation of osteomyelitis." (PMID 33868316, 2021).
osteoporosis (4 papers, 2019 to 2026). A condition of reduced bone mass, with decreased cortical thickness and a decrease in the number and size of the trabeculae of cancellous bone (but normal chemical composition), resulting in increased fracture incidence. "Among the top significantly up-regulated genes, we identified Cxcl2, an inflammatory factor associated with osteoporosis and inflammation development." (PMID 38758783, 2024). "In fact, osteoblasts in ovariectomized mice were shown to express increased levels of CXCL2 compared to sham operated controls, while injection of a neutralizing anti-CXCL2 antibody into the femoral cavity of these mice alleviated osteoporosis." (PMID 31572390, 2019).
osteosarcoma (4 papers, 2018 to 2024). A usually aggressive malignant bone-forming mesenchymal neoplasm, predominantly affecting adolescents and young adults. "Specifically, miR-532-5p has been previously documented as a prognostic marker of osteosarcoma owing to its ability to inhibit the malignant phenotype of osteosarcoma by targeting chemokine ligand-2 (CXCL2)." (PMID 34660257, 2021).
renal cell carcinoma (4 papers, 2020 to 2023). "While human TNBC and renal cell carcinoma (RCC) cells express high levels of CXCR2 ligands including CXCL1 and CXCL2, a lack of CXCR2 expression by activated NK cells can limit their migration towards these tumors." (PMID 38022679, 2023).
sarcoidosis (4 papers, 2015 to 2025). Sarcoidosis is a multisystemic disorder of unknown cause characterized by the formation of immune granulomas in involved organs. "Among those dysregulated transcripts, we validated 46 in TB and 44 in sarcoidosis, 14 of them differentially expressed in lung, 30 in lymph nodes and 4 genes dysregulated in both tissues ADAMST1, CXCL2, CXCL9, FABP4." (PMID 33276795, 2020). "We have identified new genomic markers for sarcoidosis, ADAMTS1, CXCL2, and NPR1." (PMID 33276795, 2020). "Only six genes (ADAMTS1, HSPB6, NR4A1, CXCL2, NPR1, ITGA9) were exclusively dysregulated in both lung and lymph node in sarcoidosis granulomas but not in CM or TB." (PMID 33276795, 2020).
sarcopenia (4 papers, 2011 to 2024). Progressive decline in muscle mass due to aging which results in decreased functional capacity of muscles. "Recent clinical work associates high plasma levels of chemokine ligand 2 (CXCL2) with chronic heart failure and sarcopenia." (PMID 38672567, 2024). "NLRP3 and Myd-88 are key orchestrators of chemotherapy-related cardiovascular diseases (CTRCD) and sarcopenia; cytotoxic properties are principally mediated by high levels of pro-inflammatory cytokines and chemokines, such as IL-1β, IL-6, IL-8, CXCL-2, TGF-β, IL-18 and others." (PMID 38672567, 2024).
abscess (3 papers, 2018 to 2024). An inflammatory process characterized by the accumulation of pus within a newly formed tissue cavity which is the result of a bacterial, fungal, or parasitic infection or the presence of a foreign body. "Our data show that iKIR enhances specifically the production of pro-inflammatory cytokines known to drive proper abscess formation and improved infection outcome (IL-1β), neutrophil recruitment (CXCL1 and CXCL2), but not monocyte recruitment (CCL2) in response to MRSA skin infection." (PMID 33690673, 2021).
acute lung injury (3 papers, 2016 to 2023). A condition of lung damage that is characterized by bilateral pulmonary infiltrates (pulmonary edema) rich in neutrophils, and in the absence of clinical heart failure. "Recent studies showed that CXCR2 (the receptor of CXCL1 and CXCL2) blockade results in impaired neutrophil recruitment in lipopolysaccharide-induced acute lung injury." (PMID 27447715, 2016).
acute respiratory distress syndrome (3 papers, 2024 to 2025). Progressive and life-threatening pulmonary distress in the absence of an underlying pulmonary condition, usually following major trauma or surgery. "In this vein, during acute respiratory distress syndrome (ARDS), recruited alveolar neutrophils and Mos/macrophages acquire a classically activated phenotype (Mo1/M1) responsible for the release of several growth factors and proinflammatory cytokines, including CXCL1, CXCL2, CXCL10, CCL2, and TNF-α." (PMID 39940787, 2025).